ISG15 (ISG15 ubiquitin like modifier)
Diseases named in the same sentence as ISG15 in open-access papers (continued):
Sharing a sentence is not in itself a finding about the gene and the disease.
HIV-1 infection (continued). "After HIV-1 infection, upregulation of a cluster of ISGs (RSAD2, ISG15, IFI44L, and IFI27), as compared to pre-SC, emerged and the expression of these ISGs remained high during the untreated course of infection." (PMID 39104769, 2024). "They found that persistent HIV-1 infection in humanized-mice led to induction of IFNs and ISGs including MX2, IFITM3, Trim22, ISG15, OAS1, and IFN regulatory factor 7 (IRF7) both in peripheral blood mononuclear cells (PBMCs) and in the spleen." (PMID 30665429, 2019). "Human ISG15 and USP18 are also induced by HIV-1 infection, type I IFNs, and genotoxic stress (18, 19, 24, 46, 57, –, 59, 65, 67, 69)." (PMID 31455647, 2019). "Aspects of the IFN-I pathway shown to be altered during productive HIV-1 infection, including IFN-I cytokines (IFNα/β), IFNAR1, and the antiviral ISGs, MHC-I, Interferon stimulated gene-15 (ISG15), and PKR, were investigated." (PMID 27613235, 2016). "In primary myeloid cells, both HIV-1 infection and the viral accessory protein Vpr have been shown to activate this pathway, resulting in increased STAT1 phosphorylation together with coordinated induction of ISG15, MX1, IFIT3/IFI44L, and OAS genes." (PMID 41226717, 2025). "To more closely approximate natural HIV-1 infection, we next investigated the role for ISG15 with and without an IFN-I prime in primary human CD4+ T cells, the physiological target of HIV-1 infection." (PMID 35333911, 2022). "Our results point to ISG15 as a predominantly positive regulator of HIV-1 infection (“a proviral ISG”) in human cells, unlike previous studies suggesting an antiviral role for ISGylation." (PMID 35333911, 2022). "In addition, significant changes were observed in the expression of coding genes involved in the host response to infection (e.g., ISG15, STAT1, OAS3, ISG20, CCL2, and MX1), confirming robust HIV-1 infection of these cells." (PMID 31551335, 2019). "We also noted that HIV-1 infection induces a prominent antiviral state in early/mid-gestation HCs, characterized by transcription and secretion of IFN-α and significantly elevated transcription of the RLRs, STAT1, STAT5, ISG15, OAS1, IFIT1, IFIT2, IFIT3, and Viperin." (PMID 34432853, 2021). "A limitation of the study is the small sample size in the group of HIV-infected progressors, which may explain why we did not observe significant upregulation of IFNA and ISG15 during the chronic phase of HIV-1 infection as reported in other studies." (PMID 28253319, 2017). "Furthermore, HERC5 and ISG15 were identified as correlates of protection from HIV-1 infection in controllers compared to non-controllers." (PMID 22093708, 2011). "While UBE2L6 is a known ISG15 ligase in innate immune response, UBE2J2 has no documented role in HIV-1 infection." (PMID 40204275, 2025). "As previously shown, HIV-1 infection of primary CD4+ T cells failed to induce or very weakly induced (in cells from donor I) type I IFN production and the IFN-responsive genes ISG15, IFIT1, and IFIT2." (PMID 37922361, 2023). "We observed a negative correlation between ISG15 and SRSF1 mRNA expression, particularly during acute HIV-1 infection." (PMID 36458014, 2022). "The determination of Pearson correlation coefficients revealed a negative correlation between ISG15 and SRSF1 mRNA expression upon acute HIV-1 infection." (PMID 36458014, 2022). "No changes were found at mRNA expression levels of ISG15 and MX1 after HIV-1 infection." (PMID 41041557, 2025).
melanoma (22 papers, 2008 to 2026). A malignant, usually aggressive tumor composed of atypical, neoplastic melanocytes. "For instance, in the context of melanoma, extracellular ISG15 produced by melanoma cells can induce the expression of E-cadherins on human dendritic cells, impairing its mobility and potentially allowing for tumor immune escape." (PMID 40719862, 2025). "In the TIL compartment, B16 melanomas treated with ADU-S100 + anti-ISG15 (vs. ADU-S100 alone) displayed a significant decrease in total CD8+ TIL content, but these T cells were enriched in the CD8+CD69+ activated phenotype." (PMID 38312842, 2024). "Our results showed that the ISG-15+CD8+ T-cell signature can discriminate between patients with good or poor prognoses in melanoma and urothelial carcinoma cohorts." (PMID 37735150, 2023). "ISG15 upregulation has been demonstrated in several types of cancer, including melanoma and lung, breast, prostate, nasopharyngeal, and oral cancers." (PMID 36319753, 2022). "ISG15 and enzymes involved in ISGylation have been demonstrated to be upregulated in many types of cancer, including melanoma and lung, breast, prostate, and hepatocellular cancers." (PMID 36319753, 2022). "The secretion of ISG15 by melanoma cells has been shown to modulate the phenotype of tumor-infiltrating DCs by inducing the expression of cadherin 1 (CDH1), which has been shown to reduce the migratory behavior of DCs in vitro." (PMID 27626310, 2016). "Consistent with a tumor suppressor role for the ISG15 system, various melanoma cell lines have increased levels of Ubp48, a ISG15 deconjugating enzyme." (PMID 27713259, 2010). "Increased expression of free and conjugated ISG15 has been exhibited in human breast, ovarian, prostate, colorectal and melanoma tumour cell lines compared with normal cell lines." (PMID 18627608, 2008). "While therapeutic STING agonism coordinately enhanced expression of the Arg2, Isg15, Nos2, and Pdl1 (Cd274) immuno-suppressive/regulatory ISGs in both melanoma models, Cox2/Ptgs2 expression was selectively upregulated by ADU-S100 treatment only in the B16 model." (PMID 38312842, 2024). "While these transcriptional profiling data cannot dissect the impact of intracellular (ISGylation-associated) vs. extracellular cytokine-like attributes on ISG15-related outcomes in melanoma patients, they are consistent with an immunoregulatory role for high expression levels of ISG15 in the TME." (PMID 38312842, 2024). "Remarkably, we found that different ISGs underlie resistance to ADU-S100 in different melanoma models, as B16 melanomas were most effectively treated with ADU-S100 + anti-PD-L1 or anti-ISG15 antibody, while BPR20 tumors were best treated with a combination of ADU-S100 + ARG2i/COX2i/NOS2i." (PMID 38312842, 2024). "Studies have reported that ISG15 induces the expression of E-cadherin in DCs in vitro, and E-cadherin is an adhesion molecule; its expression can impair DC motility and act as a mechanism of melanoma tumor escape." (PMID 37158921, 2023). "ISG15 secretion from melanoma cells induces E-cadherin expression, which modulates the phenotype of tumor-infiltrating DCs and leads to tumor escape, suggesting the protumoral role of unconjugated ISG15 in cancer immunogenicity." (PMID 36319753, 2022). "Demonstrating both cytokine- and chemokine-like properties when secreted by melanomas, secreted ISG15 might be considered a more practical therapeutic target for augmenting currently available anticancer treatment strategies." (PMID 27626310, 2016). "Cell culture experiments have shown that monocyte-derived DCs can be activated by secreted ISG15 isolated from the media of melanoma cell lines, and that the addition of anti-ISG15 antibodies to the medium inhibited the expression of CDH1, a marker of DC activation." (PMID 27626310, 2016).
melanoma (continued). "In mouse malignant melanoma cell lines B16F10 and Yummer1.7, knockdown of USP35 by shRNAs, which specifically targeted USP35 mRNA, significantly enhanced VSV virus-induced expression of inflammation and antiviral-associated factors, including IFNβ, CXCL10, and ISG15." (PMID 40016186, 2025). "Furthermore, melanoma shed ISG15 has been reported to promote E-cadherin expression on DCs which may negatively impact the migratory behavior of these potent APCs important for T cell crosspriming in tumor-draining lymph nodes." (PMID 38312842, 2024). "However, future studies are needed to determine the effects of melanoma-secreted ISG15 on local DC migration and T cell cytotoxicity to determine whether secreted ISG15 contributes to melanoma progression and metastasis." (PMID 27626310, 2016). "In melanoma, the STING agonist ADU-S100 can significantly induce the expression of ISG15, while neutralizing ISG15 can enhance the maturation of dendritic cells and the activation of CD8+ T cells." (PMID 41193953, 2025). "Mice bearing either B16 (BRAFWTPTENWT) or BPR20 (BRAFV600EPTEN-/-) melanomas were treated with STING agonist ADU-S100 plus various inhibitors of ARG2, COX2, NOS2, PD-L1, or ISG15." (PMID 38312842, 2024). "Representative genes from this gene set such as Rsad2, Ifih1, Isg15, Ifit1 and Tmem173 were consistently found to be upregulated in all available NRF2 knockout melanomas." (PMID 32978520, 2020). "Additionally, some tumor cells, such as human melanoma cells and nasopharyngeal carcinoma (NPC) cells, are highly active in secreting ISG15." (PMID 40719862, 2025). "In contrast, the growth of established BPR20 melanomas treated with ADU-S100 + anti-ISG15 antibody appeared indistinguishable from treatment with ADU-S100 alone." (PMID 38312842, 2024). "Conversely, i.t. administration of ADU-S100 together with systemic oral delivery of ARG2i/COX2i/NOS2i (but not i.p. anti-PD-L1 or i.t. anti-ISG15) provided superior anti-tumor efficacy vs. ADU-S100 alone in the BPR20 (BRAFV600EPTEN-/-) melanoma model." (PMID 38312842, 2024). "Among these known regulators, DTX3L drew our interest as it activates expression of ISG15 and other IFN-responsive genes by regulating the mono-ubiquitination of histones and has been found to function as an oncogenic factor in metastasis of melanoma." (PMID 29350614, 2018). "Over-expression of SOCS proteins in melanoma cell lines led to significant inhibition of Tyr701-phosphorylated STAT1 (P-STAT1) and gene expression following stimulation with IFN-α (IFIT2, OAS-1, ISG-15) or IFN-γ (IRF1)." (PMID 20398276, 2010). "Higher expression of ISG15 in CRC confronts patients with worse survival rate, and ISG15 is also up‐regulated in melanomas that are not sensitive to ICI treatment." (PMID 39934971, 2025). "In the B16 melanoma model, we noted improved antitumor efficacy only when ADU-S100 was combined with neutralizing/blocking antibodies against PD-L1 or ISG15, but not inhibitors of ARG2, COX2, or NOS2." (PMID 38312842, 2024). "Conversely, in the BPR20 melanoma model, improved tumor growth control vs. ADU-S100 monotherapy was only observed when combining ADU-S100 with ARG2i, COX2i, and NOS2i, but not anti-PD-L1 or anti-ISG15." (PMID 38312842, 2024).
ovarian carcinoma (22 papers, 2008 to 2025). A malignant neoplasm originating from the surface ovarian epithelium. "Therefore, we inferred that ISG15 was downregulated by KLF12 via binding with the CACCC element in cisplatin‐resistant ovarian cancer cells, implicated in maintenance of CSC‐like features." (PMID 33797839, 2021). "Furthermore, low ISG15 expression was associated with poor prognosis in patients with ovarian cancer." (PMID 33797839, 2021). "Follow up studies on the relationship between BRCA mutation status and ISG15 expression levels in ovarian cancer cells may help us to understand the underlying genetic components that drive ISG15 expression." (PMID 30469497, 2018). "To test this hypothesis, we first determined whether there is any association between ISG15 expression in ovarian cancer cells and CD335 (NKp46) positive NK cell number in ovarian tumor tissues." (PMID 30469497, 2018). "Aberrant expression of ISG15 has been demonstrated in most human malignancies, including ovarian cancer, suggesting it has a pro‐tumour function." (PMID 38939897, 2024). "Our study has demonstrated that the augmented release of vesicles from ascites cells and the presence of ISG15 within these vesicles can serve as potential biomarkers for evaluating clinical prognosis in ovarian cancer." (PMID 38939897, 2024). "In the current study we sought to determine the role of ISG15 in regulating ovarian cancer progression and metastasis by studying the effects of ISGylation on EV release, which are critical for the spread of ovarian cancer." (PMID 38939897, 2024). "For instance, reduced ISG15 expression in ovarian cancer seems related to a poor prognosis for patients with this disease." (PMID 37711589, 2023). "In contrast, the inhibition of ISG15 expression in cisplatin-sensitive ovarian cancer cells induces CSC-like features." (PMID 35455671, 2022). "Significant decrease in the luciferase activity of the reporter construct with ISG15 promoter (pISG15‐luc construct) was observed in SKOV3/DDP cells, inferring that ISG15 promoter recruited negative regulators in cisplatin‐resistant ovarian cancer cells." (PMID 33797839, 2021). "Consistent with the phenomena observed in lung cancer, we currently reported that significant decrease in ISG15 was observed in cisplatin‐resistant ovarian cancer cell lines." (PMID 33797839, 2021). "Together, ISG15 mRNA decreased at both transcriptional activation and post‐transcriptional stability in cisplatin‐resistant ovarian cancer cells." (PMID 33797839, 2021). "ISG15 expression was suppressed at transcriptional level, as well as post‐transcriptional levels in cisplatin‐resistant ovarian cancer cells." (PMID 33797839, 2021). "ISG15 expression was also analysed by immunohistochemical staining in different epithelial ovarian cancer tissue microarray, including serous adenocarcinoma, mucinous carcinoma, endometrial carcinoma, clear cell carcinoma and transitional cell carcinoma." (PMID 33797839, 2021). "Firstly, to confirm the potential transcriptional suppression of ISG15 in cisplatin‐resistant ovarian cancer cells, the potential ISG15 promoter was cloned into a promoter‐free luciferase reporter construct." (PMID 33797839, 2021). "The ubiquitin‐like protein interferon‐stimulated gene 15 (ISG15) was decreased in cisplatin‐resistant ovarian cancer cells." (PMID 33797839, 2021). "The apparent discrepancy is likely due to the fact that HGSOCs have a more active pro-inflammatory microenvironment with immune cells producing high levels of pro-inflammatory cytokines that up-regulates ISG15 in ovarian cancer cells." (PMID 30469497, 2018). "While both studies showed that ISG15 is a potential positive prognostic marker for ovarian cancer, the prognostic significance of ISG15 expression cannot be confirmed by analyzing the TCGA Agilent microarray dataset using cBioPortal." (PMID 30469497, 2018).
ovarian carcinoma (continued). "We demonstrated that increased ovarian cancer cell-derived ISG15 production inhibited ovarian cancer growth by suppressing ERK activity through ISGylation in an autocrine manner." (PMID 30469497, 2018). "We observed a significant correlation between increased ISG15 expression in ovarian cancer cells and increased intraepithelial CD8+ lymphocyte density in ovarian tumor tissue." (PMID 30469497, 2018). "Our data showed that intracellular ISG15 modulated the aggressive phenotype of ovarian cancer cells through inactivation of ERK1 by increasing ERK1 ISGylation in ovarian cancer cells." (PMID 30469497, 2018). "Results of Western blot analyses demonstrated a significant decrease in the levels of Tyr204 phospho-p44 ERK expression in ISG15 transfected OVCA5 ovarian cancer cells when compared to mock transfected cells." (PMID 30469497, 2018). "Further functional studies showed that endogenous and exogenous ISG15 suppressed ovarian cancer progression through ISGylation of ERK in HGSOC, and activation of NK cells and CD8+ T lymphocytes." (PMID 30469497, 2018). "We demonstrated that over-expression of ISG15 is associated with improved ovarian cancer patient survival, and overexpression of ISG15 suppressed ovarian cancer growth and increased ovarian cancer apoptosis." (PMID 30469497, 2018). "The association is further confirmed in a separate validation set of specimens, which demonstrated that ISG15 protein expression levels in ovarian cancer cells indeed correlate with number of CD8+ tumor infiltrating lymphocytes." (PMID 30469497, 2018). "In the context of HGSOC epithelia, high levels of endogenous ISG15 expression in ovarian cancer cells indeed play a tumor suppressor role." (PMID 30469497, 2018). "Recently, microarray experiments determined strong deregulation of ISG15 expression in response to diverse cancer chemotherapeutic agents, for example, paclitaxel in the treatment of ovarian carcinomas or 5-fluorouracil in the therapy of oesophageal cancer." (PMID 18627608, 2008). "Also, we analysed the ISGylation profiles and ISG15 levels in ascites derived primary ovarian cancer cells (POCCs) by western blot." (PMID 38939897, 2024). "Our findings suggest that ISG15 is a potential therapeutic target for inhibiting progression and metastasis in HGSOC and that vesicular ISG15 expression could be a promising biomarker in the clinical management of ovarian cancer." (PMID 38939897, 2024). "However, it has been unclear how ISG15 contributes to increased sEV secretion and how this, combined with the release of vesicular oncogenic proteins, impact the ovarian cancer progression and metastasis." (PMID 38939897, 2024). "In addition, the expression of ISG15 and ISGylation in metastasis tissue were significantly increased than in the primary ovarian cancer tissue of our orthotopic mice model studies." (PMID 38939897, 2024). "To determine whether ISG15 expression and ISGylation play a role in ovarian cancer tumorigenesis, we measured the expression of ISG15 in the primary ovarian tumours and ascites of patients with HGSOC by ELISA." (PMID 38939897, 2024). "While ISG15 expression is downregulated in cisplatin-resistant ovarian cancer cells, overexpression of wild-type ISG15 increases cisplatin-sensitivity of ovarian cancer cells through ISGylated hnRNPA2B1 blockage of its recruitment, and consequently, decreases MRP2/ABCC2 translation and expression." (PMID 37391814, 2023). "A recent study showed that ISG15 suppresses the translation of multidrug resistance-associated protein 2 (MRP2/ABCC2) via ISGylation of hnRNPA2B1 and enhances drug sensitivity in cisplatin-resistant ovarian cancer cells." (PMID 37391814, 2023). "Nevertheless, ISG15-dependent antitumor activities, including the reduction of proliferation, tumor growth, and the induction of apoptosis, have been reported in some cancers, such as ovarian cancer and leukemia." (PMID 37711589, 2023).